SUCLG1 (succinate-CoA ligase GDP/ADP-forming subunit alpha)
Description:
Succinyl-CoA synthetase functions in the citric acid cycle (TCA), coupling the hydrolysis of succinyl-CoA to the synthesis of either ATP or GTP and thus represents the only step of substrate-level phosphorylation in the TCA. The alpha subunit of the enzyme binds the substrates coenzyme A and phosphate, while succinate binding and specificity for either ATP or GTP is provided by different beta subunits (By similarity). Also able to act as an itaconyl- and malyl-CoA synthetase.
Synonyms: GALPHA; MTDPS9; SUCLA1
Tractability: Small molecule: a structure with a bound ligand is known. Antibody: the Human Protein Atlas places it where antibodies can reach. PROTAC: ubiquitination databases record sites on it; its protein half-life has been measured.
Target class: Enzyme; Ligase
Gene: Protein-coding gene on chromosome 2 (84,423,528 to 84,460,045, reverse strand). Ensembl gene ENSG00000163541.
Subcellular location: Mitochondrion
Subcellular location (Human Protein Atlas): Mitochondria; Cytosol; Plasma membrane
Pathways (Reactome):
Metabolism: Citric acid cycle (TCA cycle)
Gene Ontology:
Molecular function: acid-thiol ligase activity; malate-CoA ligase activity; protein binding; RNA binding; succinate-CoA ligase (ADP-forming) activity; succinate-CoA ligase (GDP-forming) activity; succinate-CoA ligase activity; catalytic activity
Biological process: malate metabolic process; toxic metabolite repair; succinyl-CoA catabolic process; tricarboxylic acid cycle
Cellular component: catalytic complex; mitochondrion; succinate-CoA ligase complex (GDP-forming); mitochondrial matrix; succinate-CoA ligase complex (ADP-forming)
Genetic constraint (gnomAD): Loss-of-function variants: 24 observed, 35.23 expected, observed/expected ratio (o/e) 0.68, 90% interval 0.49 to 0.96. The upper end of that interval is the gene's LOEUF score, 0.96, which puts it in group 4 of 6, group 1 being the genes least tolerant of losing a copy. Missense variants: 427 observed, 441.2 expected, observed/expected ratio (o/e) 0.97, 90% interval 0.89 to 1.05. Synonymous variants: 161 observed, 159.08 expected, observed/expected ratio (o/e) 1.01, 90% interval 0.89 to 1.15.
Gene-disease validity (ClinGen):
ClinGen rates the evidence that SUCLG1 causes each of these diseases.
Leigh syndrome (autosomal recessive): Moderate. A progressive neurological disease defined by specific neuropathological features associating brainstem and basal ganglia lesions.
Homologues: Orthologues: chimpanzee SUCLG1 (99% identical), macaque SUCLG1 (99% identical), dog SUCLG1 (95% identical), rabbit SUCLG1 (94% identical), guinea pig SUCLG1 (92% identical), mouse Suclg1 (92% identical), pig SUCLG1 (91% identical), rat Suclg1 (88% identical), tropical clawed frog suclg1 (80% identical), zebrafish suclg1 (80% identical), Caenorhabditis elegans sucl-2 (65% identical), Drosophila melanogaster Scsalpha1 (65% identical), and 2 more.